POLR2H (RNA polymerase II, I and III subunit H)
Description:
DNA-dependent RNA polymerase catalyzes the transcription of DNA into RNA using the four ribonucleoside triphosphates as substrates. Common component of RNA polymerases I, II and III which synthesize ribosomal RNA precursors, mRNA precursors and many functional non-coding RNAs, and small RNAs, such as 5S rRNA and tRNAs, respectively.
Synonyms: RPB8; RPABC3; RPB17
Tractability: Small molecule: a structure with a bound ligand is known. PROTAC: ubiquitination databases record sites on it; its protein half-life has been measured.
Gene: Protein-coding gene on chromosome 3 (184,360,856 to 184,368,596, forward strand). Ensembl gene ENSG00000163882.
Subcellular location: Nucleus; Nucleus, nucleolus
Subcellular location (Human Protein Atlas): Nucleoplasm
Pathways (Reactome):
Gene expression (Transcription): B-WICH complex positively regulates rRNA expression; Formation of RNA Pol II elongation complex; Formation of the Early Elongation Complex; MicroRNA (miRNA) biogenesis; NoRC negatively regulates rRNA expression; PIWI-interacting RNA (piRNA) biogenesis; RNA Pol II CTD phosphorylation and interaction with CE; RNA Polymerase I Promoter Escape; RNA Polymerase I Transcription Initiation; RNA Polymerase I Transcription Termination; RNA Polymerase II Pre-transcription Events; RNA Polymerase II Promoter Escape; RNA Polymerase II Transcription Elongation; RNA Polymerase II Transcription Initiation; RNA Polymerase II Transcription Initiation And Promoter Clearance; RNA Polymerase II Transcription Pre-Initiation And Promoter Opening; RNA Polymerase III Abortive And Retractive Initiation; RNA Polymerase III Chain Elongation; RNA Polymerase III Transcription Initiation From Type 1 Promoter; RNA Polymerase III Transcription Initiation From Type 2 Promoter; RNA Polymerase III Transcription Initiation From Type 3 Promoter; RNA Polymerase III Transcription Termination; RNA polymerase II transcribes snRNA genes; Transcriptional regulation by small RNAs
Disease: Abortive elongation of HIV-1 transcript in the absence of Tat; Dengue Virus-Host Interactions; Formation of HIV elongation complex in the absence of HIV Tat; Formation of HIV-1 elongation complex containing HIV-1 Tat; Formation of the HIV-1 Early Elongation Complex; HIV Transcription Initiation; HIV elongation arrest and recovery; Pausing and recovery of HIV elongation; Pausing and recovery of Tat-mediated HIV elongation; RNA Pol II CTD phosphorylation and interaction with CE during HIV infection; RNA Polymerase II HIV Promoter Escape; Signaling by FGFR2 IIIa TM; Tat-mediated HIV elongation arrest and recovery; Tat-mediated elongation of the HIV-1 transcript; Transcription of the HIV genome
and 15 more pathways
Gene Ontology:
Molecular function: single-stranded DNA binding; DNA-directed RNA polymerase activity
Biological process: termination of RNA polymerase III transcription; transcription by RNA polymerase II; transcription by RNA polymerase III; transcription elongation by RNA polymerase I; transcription elongation by RNA polymerase II; transcription initiation at RNA polymerase II promoter; transcription initiation at RNA polymerase III promoter; nucleolar large rRNA transcription by RNA polymerase I; termination of RNA polymerase I transcription; transcription initiation at RNA polymerase I promoter; DNA-templated transcription
Cellular component: nucleus; protein-DNA complex; RNA polymerase I complex; RNA polymerase II, core complex; RNA polymerase III complex; cytosol; nucleoplasm; nucleolus
Genetic constraint (gnomAD): Loss-of-function variants: 0 observed, 4.63 expected, observed/expected ratio (o/e) 0, 90% interval 0 to 0.65. That is too few expected variants to judge how well the gene tolerates losing a copy. Missense variants: 41 observed, 79.33 expected, observed/expected ratio (o/e) 0.52, 90% interval 0.4 to 0.67. Synonymous variants: 33 observed, 35.57 expected, observed/expected ratio (o/e) 0.93, 90% interval 0.7 to 1.24.
Homologues: Orthologues: chimpanzee POLR2H (100% identical), mouse Polr2h (100% identical), rabbit POLR2H (100% identical), guinea pig POLR2H (99% identical), tropical clawed frog polr2h (98% identical), zebrafish polr2h (97% identical), pig POLR2H (85% identical), macaque POLR2H (83% identical), rat Polr2h (81% identical), dog POLR2H (81% identical), Drosophila melanogaster Polr2H (78% identical), Caenorhabditis elegans rpb-8 (63% identical).
Diseases named in the same sentence as POLR2H in open-access papers:
POLR2H is named in the same sentence as 13 diseases in open-access papers, as found by Europe PMC text mining. Sharing a sentence is not in itself a finding about the gene and the disease. The quoted sentences say what the papers report.
prostate carcinoma (3 papers, 2020 to 2025). A carcinoma that arises from epithelial cells of the prostate gland. "POLR2H was reported to be associated with the progression of prostate cancer." (PMID 32285560, 2020).
rectal tumor (2 papers, 2020 to 2022). "We identified a group of genes of the biosynthetic machinery as rectal tumor organoid-specific, including those encoding the RNA polymerase II subunits POLR2H and POLR2J." (PMID 32824266, 2020). "Compared the gene profiling of organoids derived from a normal rectum and rectal tumors and their responses to calcitriol; Identified rectal tumor organoid-specific genes associated with biosynthetic machinery, including those encoding the RNA polymerase II subunits POLR2H and POLR2J." (PMID 35957894, 2022). "We observed that POLR2H and POLR2J are exclusively overexpressed in rectal tumor organoids." (PMID 32824266, 2020).
alcohol (1 paper, 2025). "In contrast, the overexpression of GLS1 with truncated variants of POLR2E or POLR2H did not affect the protective effects of GLS1 on alcohol‐induced fatty liver." (PMID 40936098, 2025). "In summary, we delineate a novel pathway in which dietary glutamine stabilizes GLS1, enabling its nuclear interaction with POLR2H/POLR2E to suppress RNA pol II activity and attenuate alcohol‐induced hepatic steatosis." (PMID 40936098, 2025). "Moreover, the overexpression of POLR2E or POLR2H, but not the truncated variants, abolishes the protective effects of GLS1 against alcohol‐induced fatty liver." (PMID 40936098, 2025).
Alzheimer ́s disease (1 paper, 2014). "Although most of the genes were involved in several of these pathways, some of them were restricted to Huntington’s disease (AP2B1, CREB3L4, POLR2H and SOD1), to Alzheimer ́s disease (NAE1, FAS) or to Parkinson’s disease (PARK7)." (PMID 24742402, 2014).
cervical cancer (1 paper, 2017). A primary or metastatic malignant neoplasm involving the cervix. "POLR2H has not been described to be associated with cervical cancer." (PMID 29312619, 2017).
fatty liver (1 paper, 2025). "Collectively, these findings demonstrate that in the liver, GLS1 ameliorates alcohol‐induced fatty liver through its interaction with POLR2H or POLR2E." (PMID 40936098, 2025). "Mechanistically, glutamine was found to stabilize GLS1, thereby promoting its interaction with RNA polymerase subunit H (POLR2H) and RNA polymerase subunit E (POLR2E), which reduced the activity of RNA pol II, affecting hepatic steatosis in AFLD." (PMID 40936098, 2025). "Our findings demonstrate that GLS1 interacts with the RNA pol II subunits POLR2H and POLR2E to modulate RNA pol II transcriptional activity, thereby promoting hepatic steatosis in AFLD." (PMID 40936098, 2025).
tumor (2 papers, 2023 to 2026). "Moreover, it was also determined that the expression ofHELLS,POLR2H, andPOLE2was significantly positively associated with tumor purity in LUSC." (PMID 37915460, 2023). "Other genes, such as ARPC3, POLR2H, WSB2, and ARL6IP5, show opposite association with response in tumor and stroma compartments, respectively." (PMID 41550766, 2026).
POLR2H also shares sentences with these, for which no sentence is quoted: cancer (1 paper); colon tumor (1); epilepsy (1); Huntington disease (1); infection (1); Parkinson disease (1).